CD47 (CD47 molecule)
Diseases named in the same sentence as CD47 in open-access papers (continued):
Sharing a sentence is not in itself a finding about the gene and the disease.
cancer (continued). "In this study, we investigated the potential of NTP, operated in our previously defined ICD-inducing regime, to alter surface CD47 on cancer cells." (PMID 33540720, 2021). "Anti-phagocytic signals are often overexpressed in cancer cells to counterbalance macrophage surveillance, and the most studied “don’t eat me” signal is the checkpoint molecule CD47." (PMID 34944878, 2021). "Cancer cells, including leukemic cells, express higher levels of CD47 as a mechanism of protection against macrophage phagocytosis." (PMID 34944878, 2021). "Blocking the interaction between CD47 and SIRPα has proven to be effective in removing cancer cells." (PMID 33629544, 2021). "These mechanistic studies are crucial to inform novel therapeutic approaches capable of differentially targeting the SIRP:CD47 signaling pathway in cancer and autoimmune disease settings." (PMID 34603322, 2021). "First, the interaction between CD47 on cancer cells and SIRPα on the surface of macrophages leads to diminished cytoskeleton activity, which is reflected by decreased non-muscle myosin and actin in the phagocytic synapse." (PMID 34944878, 2021). "CD47 is a unique 5-TM receptor with multiple biological functions and a validated drug target in cancer immuno-therapy." (PMID 34471125, 2021). "Combining the CD47 blocking domain, such as endogenous SIRPα, with a cancer-specific antibody in a single molecule can restrict the blockade of CD47 locally on antigen-expressing cells." (PMID 34579739, 2021). "It will be very interesting to apply methods for simultaneous profiling of protein and mRNA expression in single cells to better understand the interplay between APA, gene expression, and membrane localization of CD47 in cancers." (PMID 34521731, 2021). "Combined with SIRPα on the surface of macrophages, CD47 on the surface of cancer cells can send an antiphagocytic “Don’t eat me” signal to the immune system that helps to avoid immune surveillance." (PMID 34805154, 2021). "And it was suggested that the affinity of IBI322 to PD-L1 was stronger than that to CD47, implying a potential therapy regime in PD-L1-positive cancers." (PMID 34305918, 2021). "In accordance with surface depletion of CD47, cancer cells exposed to BoxA are readily phagocytosed by macrophages." (PMID 34561422, 2021). "An interesting example is RRx-001, which downregulates CD47 on cancer cells and SIRPα on monocytes and stimulates TAMs against cancer cells." (PMID 33919517, 2021). "Lipid-based NPs can increase anti-cancer efficacy by binding to SIPRα on macrophages and CD47 on cancer cells, at the same time as inhibiting CD47-SIRPα signalling pathway involved in the “do not eat me” signal." (PMID 35186955, 2021). "The role of the CD47/SIRPα interaction in providing an escape mechanism for cancer cells from macrophage targeting has been well described." (PMID 34944850, 2021). "Therapeutic approaches currently focus on inhibiting the CD47-SIRPa binding to activate phagocytosis of cancer cells and several small and large molecule inhibitors are undergoing clinical investigations." (PMID 33805268, 2021). "SIRPα (signal-regulatory protein α)/CD47 immune checkpoint is “don’t eat me” signal, which inhibits phagocytosis of cancer cells by macrophage." (PMID 34493296, 2021). "In TNBC, anti-CD47 antibody inhibited the differentiation of cancer stem cells (CSC) and down-regulated the expression of EGFR." (PMID 34717710, 2021). "In contrast to the restricted expression of SIRPα, CD47 is expressed on both healthy and cancer cells." (PMID 34717705, 2021). "More studies should be performed to elucidate the respective role(s) of CD47 in different cancer types so as to optimize potential anti-CD47 therapy." (PMID 33765961, 2021). "In a clinical setting, several approaches to block CD47-SIRPα axis are already in clinical development for multiple cancer indications." (PMID 34503071, 2021).
cancer (continued). "Elevated CD47 expression in cancer cells counteracts their pro-phagocytic signals and CD47 blockade is considered a valid target for immunotherapy." (PMID 34145398, 2021). "Such modulatory effects of Gal-9 on PS and CD47 expression were similarly detected in various other carcinoma cell lines." (PMID 35052746, 2021). "Here, we describe a combination strategy of black phosphorus (BP)-based photothermal therapy together with anti-CD47 antibody (aCD47)-based immunotherapy to synergistically enhance cancer treatment." (PMID 33014356, 2020). "The aim of this review is to highlight the current literature and research on CD47, provide an impetus for investigation of its blockade in pediatric cancer histologies, and provide a rationale for new combination therapies in these patients." (PMID 35582455, 2020). "The combination of innate and adaptive immunotherapy has the potential to overcome known resistance mechanisms in cancer, such as CD47 overexpression." (PMID 35582455, 2020). "Another strategy has reported the efficacy of small molecular weight agents targeting the synthesis and trafficking of CD47 in cancer cells." (PMID 33552071, 2020). "M2-conditioned medium induces CD47 expression in cancer cells, and M2 macrophages express more SIRPα and migrate to CD47+ cells faster, while CD47+ cancer cells invade more quickly in the presence of M2 macrophages." (PMID 35582455, 2020). "An interesting strategy aims to enhance TAM phagocytic properties blocking the CD47/SIRPα ‘don’t eat’ signal by target cancer cells that express CD47 at high levels as an acquired mechanism of resistance to clearing by phagocytosis." (PMID 32708142, 2020). "CD47, an immune checkpoint known as the “don’t eat me” signal, is highly expressed on the surface of various cancers, allowing cancer cells to send inhibitory signals to macrophages and impede phagocytosis and immune response." (PMID 32012878, 2020). "CD47 is overexpressed in many types of human cancer cells and protects them from being recognised and cleared by innate immune surveillance." (PMID 33574894, 2020). "CD47-SIRPα interactions form an innate immune checkpoint and its targeting has shown promising results in cancer patients." (PMID 33162986, 2020). "Hematological cancer cells overexpress CD47 in order to evade removal by phagocytes (macrophages and dendritic cells)." (PMID 32457743, 2020). "We used CRISPR-modified HAP1 cells, which are commonly used for loss of function genetic screens, transduced 49 with Cas9 and a single-guide RNA (sgRNA) targeting CD47, a cell surface protein responsible for immune evasion in cancer." (PMID 33177493, 2020). "Overexpression of CD47 increases the net antiphagocytic signal and appears to be a general mechanism used by cancer cells to evade phagocytosis." (PMID 32281289, 2020). "In one study, using anti-CD47 antibodies to inhibit the CD47−SIRPα interaction activated innate immunity by promoting the destruction of cancer cells by macrophages." (PMID 33178201, 2020). "In another study, microRNA 222 (miR-222) was found to negatively regulate CD47 expression, and overexpression of miR-222 enhanced cancer cell radiosensitivity via the CD47-pERK pathway." (PMID 35582455, 2020). "Firstly, by cell to cell contact through CD47 (cancer cell) and SIRPα (macrophage) binding, CCR2, or CX3CR1 chemokine receptors; Secondly, through soluble factors or exosomes loaded in IL-10." (PMID 32477352, 2020). "CDC42 is a member of the Rho family of small GTPases and is activated by CD47 to serve as a crucial regulator of cancer metastasis." (PMID 32314789, 2020). "A growing body of evidence demonstrates that CD47 is overexpressed in various hematological malignancies and its interaction with SIRPα on the phagocytic cells prevents phagocytosis of cancer cells." (PMID 32677994, 2020).
cancer (continued). "The expression levels of JUN, SFN, HSPB1, and CD47 in cancer cells and the expression levels of KLRB1, CD48, GZMK, and LY6E in CD8+ T cells were consistent with the scRNA-seq results." (PMID 33083004, 2020). "Noticeably, it has been identified that CD47 induces the immunological evasion of cancer cells, and is considered as a potential target for cancer treatment." (PMID 32314789, 2020). "Blockade of the CD47–SIRPα interaction represents a promising approach to boost the antitumor activity of cancer immunotherapies when used as an adjuvant in antitumor antibody or ICI therapy." (PMID 33256806, 2020). "One of the best established in this respect is the overexpression of the “don’t eat me” signal CD47 in cancers." (PMID 33105656, 2020). "Synergetic benefits of targeting multiple receptors are being evidenced including simultaneous blocking of CD47 and PD-L1 in cancer immune responses and cytokine release55and dual antibody blockade of CD39 and CD73 combined with ICIs and chemotherapies." (PMID 32929084, 2020). "Blocking the CD47-SIRPα interaction has been shown to promote the destruction of cancer cells by phagocytes, including macrophages and neutrophils." (PMID 32944390, 2020). "Professional antigen presenting cells (APCs) are deterred from phagocytosing cancer cells that express CD47." (PMID 32198351, 2020). "On average, essentially all cancers express CD47 mRNA, mostly ranging 2-8 log2 (4-256 TPM for all genes)." (PMID 35582455, 2020). "Accumulating evidence suggests that cancer cells can impair the immune system and evade phagocytosis by macrophages via the activation of CD47 signaling." (PMID 32149101, 2020). "More recently, this strategy in combination with CD47 antagonists has been considered to inhibit cancer recurrence and metastasis effectively." (PMID 31947622, 2020). "In preclinical cancer models, the pharmacological inhibition of CD47, overexpressed by cancer cells, restores the ability of macrophages to phagocyte and kill tumor cells." (PMID 33050070, 2020). "Collectively, these findings highlight a potent antitumor effect of SG635‐SF in the treatment of CD47‐positive cancers." (PMID 31899582, 2020). "Among them, CD47 is an essential key anti-phagocytic molecule in carcinogenesis and is known to prevent the elimination of cancer cells by macrophages." (PMID 32286430, 2020). "CD47 has been identified as one of the most important anti-phagocytic “don’t eat me” signals, owing to its upregulation on many different types of human cancer cells." (PMID 33603751, 2020). "4T1 cells treated with Dox also increased expression of the anti-phagocytic marker CD47, previously demonstrated to aid in immunoevasion by cancer cells." (PMID 33173046, 2020). "The released anti-CD47 antibody blocks the ‘don’t eat me’ signal in cancer cells, thereby increasing phagocytosis of cancer cells by macrophages." (PMID 31947622, 2020). "Its ligand, the “don’t eat me” signal CD47, is broadly expressed on the plasma membrane of essentially all cell types and is often overexpressed on cancer cells." (PMID 32944390, 2020). "It is known that cancer cells express the CD47 receptor to manipulate macrophages that escape immune surveillance; blockage of the CD47/signal regulatory protein alpha (SIRPα) axis increases phagocytosis of cancer cells and immune responses." (PMID 32486019, 2020). "Essentially, this represents a process that translates into an abundant activation of the immune cells, which allows enhancement of the anti-CD47 therapy by increasing its ability to destroy cancer cells." (PMID 33013813, 2020). "In this scenario, phagocytosis of cancer cells by TAMs provides additional antitumour activity, which, however, is impaired by the ‘don’t eat’ me signal CD47, expressed by many cancer cells." (PMID 33574894, 2020).
cancer (continued). "Recent studies have demonstrated that neutrophil ADCC toward cancer cells occurs through a mechanism called trogocytosis, which can be further improved by targeting CD47-SIRPα interactions." (PMID 33329583, 2020). "This approach synergizes with CD47 blocking, amplifying PrCR and yielding potent anti-cancer activity." (PMID 33603751, 2020). "As is mentioned in a recent study, glutaminyl-peptide cyclotransferase-like protein (QPCTL) is identified as a new target to interfere with the CD47 pathway and promotes the efficacy of antibody therapy of cancer." (PMID 32161718, 2020). "Recently, research has revealed the critical role played by CD47, which is a widely expressed protein present on the surface of many cancer cells triggering a deleterious signal to the macrophages inviting them not to attack." (PMID 33013813, 2020). "For example, decreased expression of CD47 on the surface of aged cells facilitates their phagocytic removal, whereas CD47 over-expression on cancer cells constitute an immune-evasion mechanism that confers a pro-survival advantage." (PMID 33224442, 2020). "In pathologic conditions, varieties of cancer cells are known to induce increased CD47 surface expression as a mechanism to evade macrophage mediated phagocytosis." (PMID 32882841, 2020). "We demonstrated that the oncolytic adenovirus SG635‐SF armed with the SIRPα‐Fc fusion gene exhibited a great inhibitory effect on CD47‐positive cancer cells both in vitro and in vivo." (PMID 31899582, 2020). "Nonetheless, the immune-independent effects of CD47 on cancer progression were observed in some recent studies." (PMID 32226539, 2020). "The upregulation of CD47 as an immune-inhibitory molecule post the question on why the host dampen its defense during cancer and infection." (PMID 32882841, 2020). "Upregulation of CD47 was observed in various cancer types and plays a vital role in escaping the immune surveillance of macrophages 9,19." (PMID 32226539, 2020). "Confocal imaging showed that CD47 blockade by SαV-C-NVs significantly increased the phagocytosis of cancer cells by BMDMs in a dose-dependent manner." (PMID 32999291, 2020). "Most of the previous studies investigating CD47 focused on the immune-suppressive effects mediated by the CD47-SIRPα axis between cancer cells and macrophages." (PMID 32226539, 2020). "Previous studies have demonstrated that the inhibition of cell proliferation and colony formation by CD47 knockdown can be attributed to the suppression of cancer stem cell character." (PMID 32149101, 2020). "We show that the uptake of cancer EV is affected by the presence of intact EV membrane surface proteins, which include CD47." (PMID 32751082, 2020). "In line with previous reports in other tumors, we found that hypoxic stimulation leads to an increase of CD47 levels on cancer cells." (PMID 32231135, 2020). "As monotherapy, interfering with the CD47–SIRPα interaction generally has limited efficacy but is a powerful adjuvant to a variety of cancer immunotherapies." (PMID 33256806, 2020). "CD47 forms a signaling complex with signal-regulatory protein α (SIRPα), enabling the escape of these cancer cells from macrophage-mediated phagocytosis." (PMID 32082311, 2020). "Recent and ongoing clinical trials are demonstrating the safety and efficacy of CD47 blockade in combination with monoclonal antibodies, chemotherapy, or checkpoint inhibitors for adult cancer histologies." (PMID 35582455, 2020). "The anti-phagocytic membrane protein CD47, which reduces uptake of cancer cells by monocytes and macrophages is also present on EV." (PMID 32751082, 2020). "Taken together, these findings provide a rational basis for targeting the interaction of CD47-SIRPα in cancer, particularly to enhance the efficiency of antibody therapy in cancer." (PMID 32161718, 2020).
cancer (continued). "Signal regulatory protein alpha (SIRPα) and CD47 have an important role during cancer progression and blocking CD47-SIRPα interaction has been shown to promote the destruction of cancer cells by phagocytes, macrophages, and neutrophils." (PMID 32210958, 2020). "It is a hint of a poor prognosis when CD47 can highly express in malignant tumors, for example, leukemia, myeloma, ovarian tumor, and so on." (PMID 33488618, 2020). "As an inhibitory protein, both the genetic knockout and blockade of CD47 results in increased activation of antigen presenting cells (APCs) during cancer and infection." (PMID 32882841, 2020). "As with most mechanisms of immunosuppression utilized for healthy homeostasis, cancer cells often co-opt CD47 overexpression to escape innate immune surveillance by counteracting these signals." (PMID 35582455, 2020). "To date, several studies have been done using several anti-CD47 antibodies in various cancer studies with insightful mechanisms of action." (PMID 32882841, 2020). "One of these receptors, CD47, also known as the “don’t eat me” signal, has been found to be overexpressed by most cancer histologies and has been successfully targeted by antibodies blocking the receptor or its ligand, signal regulatory protein α (SIRPα)." (PMID 35582455, 2020). "Massive studies have shown that overexpression of CD47 predicts poor prognosis and promotes cancer cell invasion in many types of cancer." (PMID 32098099, 2020). "The disruption of CD47/SIRPa-signaling increases macrophage mediated phagocytosis of diseased vascular tissue and cancer cells." (PMID 32882841, 2020). "CD47 is over-expressed on the cancer cell surface, which enables escape from immune system recognition by labeling the cells with the “self” marker." (PMID 31903120, 2020). "A typical scenario would see CD47 (“don’t eat me” signal) expressed on a cancer cell bind to SIRPα on an immune effector (e.g. macrophage) causing an inhibitory signal in the effector cell which dampens phagocytosis." (PMID 33552071, 2020). "Our results reveal a strategy of activating PrCR independent of and complementary to current PrCR-based therapies by blocking CD47 on cancer cells." (PMID 33603751, 2020). "Taking advantage of this anti-phagocytic signal provided by CD47, many types of tumors overexpress this protein, thereby avoiding phagocytosis by macrophages and aiding in the survival of cancer cells." (PMID 33015199, 2020). "This ‘self’ signal has been revealed to form part of the host immune‐escape strategy of malignant cells by high‐expressing CD47; that is, the ‘self’ signal is harnessed as a ‘don't eat me’ signal to allow the cancer cell to escape from the host immune system." (PMID 31899582, 2020). "At this time, TAMRA DN1K on MoS2 nanosheets combined with CD47 on cell surface, realizing the fluorescence imaging of the cancer cells or tissues with high expression of CD47." (PMID 32318550, 2020). "CD47, the “don't eat me” signal, is an important immune checkpoint inhibitor that contributes to the progression of cancer." (PMID 32984001, 2020). "It has also been shown that disruption of the TSP-1/CD47 interaction has positive outcomes in cancer therapy." (PMID 32677994, 2020). "The “don’t eat me” signal CD47 is a self-molecule expressed by cancer cells that protects them from phagocytosis by binding to the signal regulatory protein (SIRP)1α on macrophages." (PMID 32823961, 2020). "CD47 expression become an interesting research area when cancer cells were known to have an increased CD47 expression as a survival mechanism and the blockade of CD47 resulted in increased phagocytosis by macrophages and suppression of many tumors." (PMID 32882841, 2020). "The anti-CD47 is currently under clinical trial for cancer and can be amenable as an immunotherapeutic target for infectious diseases." (PMID 32882841, 2020).